CACNA1C (calcium voltage-gated channel subunit alpha1 C)
Diseases named in the same sentence as CACNA1C in open-access papers (continued):
Sharing a sentence is not in itself a finding about the gene and the disease.
psychosis (13 papers, 2014 to 2025). "CACNA1C, one of the most consistently associated GWAS loci across mood and psychotic disorders, encodes an L-type voltage-gated calcium channel critical for neuronal excitability and synaptic function." (PMID 40295477, 2025). "Differential methylation of genes including CACNA1C have also been found in patients with psychosis in an Epigenome-Wide Association Study (EWAS)." (PMID 36803254, 2023). "Rare and structural variants in CACNA1C have also been reported in psychosis, and rare variants in CACNA1C and CACNA1D identified in other neurodevelopmental syndromes." (PMID 36154842, 2022). "However, more studies of PTSD with comorbid psychotic disorders need to be undertaken to confirm any association with CACNA1C or other epigenetic markers." (PMID 30781888, 2019). "The CpG at the intronic position cg01833890 in CACNA1C was found to be differentially methylated in patients exhibiting psychosis." (PMID 36803254, 2023). "CACNA1C encodes a subunit of a calcium channel essential for neuron action potentials and has been implicated in MDD and the psychotic disorders (bipolar disorder and schizophrenia)." (PMID 30781888, 2019). "Also, a high degree/likelihood of replication was found for the two GWAS- (ZNF804A and CACNA1C) and one candidate-implicated (BDNF) SNPs, which supports their involvement in psychosis and brain structure." (PMID 36168994, 2022). "Seven psychosis-implicated SNPs across five different genes (proxies of ZNF804A-rs1344706, CACNA1C-rs1006737, BDNF-rs6265, DISC1-rs2793092, DISC1-rs11122319, NRG1-rs6994992 and NRG1-rs35753505 itself) were examined in our independent sample for effects on brain volume." (PMID 36168994, 2022). "We show that rats hemizygous for Cacna1c harbour marked impairments in learning to disregard non-salient stimuli, a behavioural change previously associated with psychosis." (PMID 33597718, 2021). "Impaired reward processing may be a transdiagnostic phenotype of variation in CACNA1C that could contribute to anhedonia and other clinical features common to both affective and psychotic disorders." (PMID 25290268, 2014).
breast carcinoma (12 papers, 2015 to 2025). "Besides, variants of CACNA1C were associated with bladder cancer, endometrial cancer and breast cancer risk." (PMID 34210324, 2021). "CACNA1C, as a voltage-gated calcium channel, is up-regulated in brain tumors, leukemia, breast cancer, and other tumors and plays as an oncogene in OC tumors." (PMID 35361267, 2022). "Previous meta-analysis results showed that CACNA1C was up-regulated in brain tumors, leukemia, breast cancer and other tumors, suggesting its regulatory roles in cancer progression." (PMID 34210324, 2021). "In line with previously published articles, CACNA1C was up-regulated in brain tumors, leukemia, breast cancer and other tumors." (PMID 34210324, 2021). "Among these, 11 CNVRs overlapped with 12 genes (GSTM2, RAB40B, HLA_DRB5, HLA_DRB6, EYA1, DOCK3, ANKS1B, CACNA1C, RAB11FIP3, BAGE, SGCZ, POM121c) and were specifically associated with breast cancer risk and OS." (PMID 29116104, 2017). "Given that CACNA1C is known to be overexpressed in breast cancer tissue, it seems that CaV1.2 and one or more of the CaV3 subfamily are involved in the regulation of Ca2+ signalling in these cells." (PMID 27342111, 2016). "For instance, breast cancer showed dramatic upregulation of CACNA1C, CACNA1D, CACNA1B, CACNA1G, and CACNA1I." (PMID 26147197, 2015). "This bioinformatics analysis revealed that different subtypes of VGCCs (CACNA1C, CACNA1D, CACNA1B, CACNA1G, and CACNA1I) are implicated in the development and progression of diverse types of cancer and show dramatic up-regulation in breast cancer." (PMID 26147197, 2015). "However, it has been reported that Cav1.2 (CACNA1C, a subunit of L-type VGCC) also participates in the progression of several cancers (breast cancer and oral squamous carcinoma) and is strongly correlated with the poor prognosis." (PMID 36057617, 2022). "Of the L-type calcium channel α1 subunits, expression of CACNA1D, CACNA1S, but not CACNA1C, was detected in MDA-MB-231 cells at the mRNA level (CACNA1F was not tested as it appeared to be often downregulated in breast cancer clinical samples)." (PMID 27910855, 2016).
Ventricular arrhythmia (12 papers, 2011 to 2025). "While prior studies hint at CACNA1C mutations’ role in ventricular arrhythmia genesis, the mechanisms, especially in G406R presence, are not fully understood." (PMID 38968219, 2024). "Previous experimental studies have shown that CACNA1C mutations can alter ICaL, potentially triggering ventricular arrhythmias." (PMID 38968219, 2024). "In this study, we focus on the mechanisms by which altered ICaL caused by a R858H CACNA1C mutation promotes and perpetuates ventricular arrhythmia using mathematical modeling." (PMID 29046645, 2017). "Thus, cardiac models provide a powerful tool for the study of mechanisms underlying ventricular arrhythmias caused by CACNA1C mutation effects." (PMID 29046645, 2017). "We conclude that the CACNA1C clinical variant mimics the increased activity associated with the upregulation of CaV1.2 by Ca2+–CaM, thus maintaining a majority of channels in a constitutively active mode that could ultimately promote ventricular arrhythmias." (PMID 36273583, 2022). "Andersen-Tawil syndrome (KCNJ2) and Timothy syndrome (CACNA1C) are rare conditions affecting multiple systems whose phenotypic expression includes QT prolongation and ventricular arrhythmias." (PMID 31983240, 2020). "The findings of this study provide new insights into the mechanism underlying the development and maintenance of VT in patients with CACNA1C G1911R mutation and emphasize the critical role of MCELL in the genesis of ventricular arrhythmias." (PMID 27502440, 2016). "For ventricular arrhythmia, many of the significant proteins identified by the diffusion algorithm are ion channel proteins, such as those that contribute to Ca2+ (CACNA1C, CACNA1C-IT2), Na+ (SCN3A, SCN1B, SCN4B, SCN10A), or K+ (KCNQ1, KCNE3, KCNH2) transport in the heart." (PMID 39954672, 2025). "Further study is necessary to fine-map these loci, identify causative variants, and elucidate their impact on CACNA1C and NOS3 function or levels, signaling, L-type calcium current, and whether they ultimately affect development of ventricular arrhythmias." (PMID 21658281, 2011).
Alzheimer disease (11 papers, 2017 to 2025). A progressive, neurodegenerative disease characterized by loss of function and death of nerve cells in several areas of the brain leading to loss of cognitive function such as memory and language. "In addition, an epigenome-wide meta-analysis of four brain sample cohorts found that several methylated CpG sites in the CACNA1C gene were significantly associated with the Alzheimer’s disease (AD) Braak stage." (PMID 40170191, 2025). "A study on late-onset Alzheimer’s disease focusing on protein–protein network interactions revealed eight genes with strong associations: APOE, SORL1, APOC1, CD33, CLU, TOMM40, CNTNAP2, and CACNA1C." (PMID 39228919, 2024). "microRNA-137 inhibits Tau hyperphosphorylation in Alzheimer’s disease and targets the CACNA1C gene in transgenic mice and human neuroblastoma SH-SY5Y cells." (PMID 32737762, 2020). "Likewise, the compromised mitophagy process has been reported to play a role in some diseases such as Alzheimer’s diseases, Parkinson’s disease and CACNA1C-related disorders." (PMID 41456028, 2025). "It has been reported that the splicing of the APP, APOE, SNCA, MAPT, DAO, SHANK3, and CACNA1C genes, which are recorded in the PsyGeNET database, were abnormal in patients with neurological diseases such as Parkinson’s disease, Alzheimer’s disease, and amyotrophic lateral sclerosis." (PMID 39858933, 2025). "These genes include CACNA1C, LRP1, PLCB2, GRIN2A, and NMUR2, which are involved in pathways such as Alzheimer’s disease, long-term potentiation, calcium signaling, and transmission across chemical synapses." (PMID 29184056, 2017).
dilated cardiomyopathy (11 papers, 2007 to 2025). Cardiomyopathy which is characterized by dilation and contractile dysfunction of the left and right ventricles. "Pertaining to Ca2+ handling abnormalities, autoantibodies targeting the N-terminus of the L-type voltage-gated Ca2+ channel (Cav1.2, α1c pore-forming subunit or CACNA1c) are present in 49% of patients with dilated cardiomyopathy." (PMID 33241446, 2020). "In the close examination, 3 genes (Itgb6, Cacna2d3, and Cacna1c) were downregulated in 2-week-old cKO hearts, compared to 15 genes downregulated in KEGG_dilated cardiomyopathy pathway in 6-week-old cKO." (PMID 31787756, 2019). "Despite not being detectable by qPCR in our samples, CACNA1C was identified in a number of our enriched DMR pathways concurrently dysregulated in the cardiac proteome including dilated cardiomyopathy and hypertrophic cardiomyopathy." (PMID 36555856, 2022). "In human hearts, we found that the mRNA level of splicing factor Rbfox1, but not Rbfox2, was downregulated in dilated cardiomyopathy, and CACNA1C mRNA level was dramatically decreased in the both of dilated and ischemic cardiomyopathy." (PMID 28949795, 2018).
hypertrophic cardiomyopathy (11 papers, 2017 to 2025). A condition in which the myocardium is hypertrophied without an obvious cause. "Changes in AS of ATP5C1, DCLK2, and MAP3K4 rewire interactions with a “Hypertrophic cardiomyopathy” pathway, and of CACNA1C, TPM3, and ITGB1 rewire interactions with the “Diabetic cardiomyopathy” pathway." (PMID 40337913, 2025). "Recently, a novel CACNA1C mutation p.R1937P was reported in a Chinese family of hypertrophic cardiomyopathy with early repolarization and SQTS, p.R1937P induced the loss-of-function of CaV1.2 channels, which dramatically decreased the ICa and hyperpolarized the SSI." (PMID 30027834, 2018). "To this end, we conducted gene enrichment analysis, and observed stronger enrichments of upregulated genes involved in hypertrophic cardiomyopathy (ADRA1A, TNNI3, MYL2) and cardiac muscle contraction (CACNA1C, CASQ2, CAMK2B)." (PMID 37084237, 2023). "Next, our KEGG analysis showed that transcripts up-regulated in the mutant cardiomyocytes were related to hypertrophic cardiomyopathy (ACTC1, MYL2, MYL3), Ca2+-dynamics regulatory pathway (ATP2B4, CACNA1C, CAMK2B, PLN), as well as cardiac-muscle contraction transcripts (ACTC1, MYH7, TNNI3, TNNT2)." (PMID 35784482, 2022).
mental disorder (11 papers, 2015 to 2024). A disease that has its basis in the disruption of mental process. "The L-type calcium channel Cav1.2 encoded by CACNA1C is a risk factor for multiple mental disorders, and the risk variant of this gene increases channel expression in human brain, and increases calcium currents in human-induced neurons." (PMID 33319854, 2021). "LTCC opening is needed to sustain neuronal firing, but high levels, such as with stress, reduce neuronal firing and impair working memory, helping to explain why both loss- and gain-of-function variants in CACNA1C were associated with impaired cognition and increased risk of mental disorders." (PMID 38776078, 2024). "Why do genetic risk studies of mental disorders find consistent associations with CACNA1C?" (PMID 38776078, 2024). "Interestingly, the genetic risk variants of mental disorders in CACNA1C act as both mQTLs and eQTLs; therefore, the genotype at these risk SNPs is associated with a variation in DNAm and expression levels of the gene." (PMID 36011346, 2022). "For example, CACNA1C is harmful in Europeans but not in East Asians, while CACNB2 is associated with a higher risk of mental disorders in East Asians." (PMID 38166843, 2024).
channelopathies (10 papers, 2012 to 2024). "Ank3 and Cacna1c, which have been associated with channelopathies and the development of neuropsychiatric disorders, also presented an upregulation in their expression levels." (PMID 38793693, 2024). "Brugada syndrome (BrS) is another channelopathy that can result from a loss of function mutation in the Cacna1c gene." (PMID 35326393, 2022). "Channelopathies associated with CACNA1C have been observed in psychiatric disorders, although these were not reported for Family A. According to the AHBA, strongest expression levels are in the thalamus." (PMID 27120335, 2016). "The variants included three channelopathy-associated genes (RYR2, CACNA1C, and ANK2), three HCM- or DCM-associated genes (MYH7, LDB3, and PRKAG2), five ACM-related genes (PKP2, JUP, DSG2, DSP, and TMEM43), and two cardiac transcription factor genes (TBX5 and GATA4)." (PMID 39272661, 2024).
Intellectual disability (10 papers, 2019 to 2025). "CACNA1C encodes the alpha 1C subunit of the Cav1.2 voltage-dependent L-type calcium channel and has been related to deficient semantic verbal fluency in SZ, as well as to executive dysfunction, intellectual disability, and ASD." (PMID 30936846, 2019). "We analyzed the allele frequencies of nine single-nucleotide polymorphisms (SNPs) in the CACNA1A, CACNA1C, and CACNA1H genes among pediatric patients with developmental delay/intellectual disability (DD/ID)." (PMID 40725423, 2025). "The high prevalence of intellectual disability in CACNA1C related disorders is explained with the role played by the calcium ion channels in both prenatal and postnatal brain development." (PMID 38790536, 2024). "In support of these findings, missense variants in CACNA1C and CACNA1D are associated with syndromic intellectual disability and common variants are associated with psychiatric disorders." (PMID 36824672, 2023).
short QT syndrome (10 papers, 2017 to 2025). "Similarly, mutations in CACNA1C alter L-type voltage-gated Ca2+-channels and are associated with long QT and short QT syndromes." (PMID 39954672, 2025). "By screening 162 probands with BrS or BrS combined with short QT syndrome (SQTS) (BrS+ SQTS), there were 7 newly identified mutations in CACNA1C, including p.E1115K, p.R1880Q, p.V2014I, p.D2130N, p.E1829_Q1833dup, p.C1873Y and p.E850del." (PMID 30027834, 2018).
attention deficit-hyperactivity disorder (9 papers, 2018 to 2024). A disorder characterized by a marked pattern of inattention and/or hyperactivity-impulsivity that is inconsistent with developmental level and clearly interferes with functioning in at least two settings (e.g. at home and at school). "For instance, a SNP located between the CACNA2D4 and CACNA1C genes (rs1024582) was significantly associated with cross-disorders that included attention deficit hyperactivity disorder (ADHD), BPD, ASD, SCZ, and MDD." (PMID 32607809, 2020). "Pathogenic variants of CACNA1C have been identified in subjects with intellectual disability, executive dysfunction, hyperactivity-impulsivity that interferes with Attention-Deficit/Hyperactivity Disorder (ADHD) and/or ASD, as well as forms of childhood-onset epilepsy." (PMID 30405489, 2018). "Both LOF and GOF CACNA1C variants have been detected in patients diagnosed with early infantile epileptic encephalopathy (EIEE), intellectual disability (ID)/global developmental delay (GDD), autism spectrum disorder (ASD), and attention deficit-hyperactive disorder (ADHD) based on recent reviews." (PMID 37448958, 2023). "Furthermore, our review has revealed CACNA1A, CACNA1C and CACNA2D1 as the candidate genes for attention deficit hyperactive disorder." (PMID 33985586, 2021).
mood disorder (9 papers, 2014 to 2025). A cognitive disorder a disturbance in which the person's mood is hypothesized to be the main underlying feature. "CACNA1C, a gene that encodes the L-type voltage-gated calcium channel, has been repeatedly associated with mood disorders, impacting neuronal excitability and plasticity." (PMID 40640508, 2025). "Similarly rats with mutations in the Cacna1c gene, putatively suffering from altered dopaminergic signalling and associated with mood disorders, produce more flat USVs." (PMID 36815182, 2023). "Thus, the CACNA1C polymorphism may preferentially predispose individuals toward mood disorder or schizoaffective phenotypes." (PMID 24944871, 2014). "CACNA1C may be associated with biological systems altered in mood disorder." (PMID 24944871, 2014). "Four of the most consistently replicated variants associated with mood disorder occur in genes important for synaptic function: ANK3 (rs10994336), BDNF (rs6265), CACNA1C (rs1006737), and DGKH (rs1170191)." (PMID 24944871, 2014). "While the present study did not replicate associations between the CACNA1C polymorphism and mood disorder, this is likely due to the need for very large samples to detect weak associations between candidate polymorphisms and neuropsychiatric diagnoses." (PMID 24944871, 2014).
migraine (8 papers, 2015 to 2024). "So, a down-regulation of CACNA1C gene could be also associated with these ionic disturbances in neuronal synapses; indicating that miR-342-3p has a reliable effect on migraine pathophysiology." (PMID 36797674, 2023). "Thus, CACNA1C is a promising candidate gene for psychiatric disorders, seizures, and migraine." (PMID 31291898, 2019).
type 2 diabetes (8 papers, 2013 to 2023). "The L-type voltage-gated Ca2+ channel genes Cacna1c and Cacna1d are essential for rodent pancreatic beta cell function and polymorphisms in Cacna1d have been associated with type 2 diabetes." (PMID 26518685, 2016). "In particular, the results of the KEGG analysis showed that CACNA1C was enriched in multiple pathways including type 2 diabetes and insulin secretion." (PMID 36901708, 2023). "Decreased expression of calcium channel-related genes such as cacna1c and cacna1d is one of the characteristics of type 2 diabetes." (PMID 34358068, 2021). "A more surprising over-represented pathway was type II diabetes (with CACNA1C from our prioritized gene list)." (PMID 32734521, 2020).
ventricular fibrillation (8 papers, 2017 to 2024). A disorder characterized by an electrocardiographic finding of a rapid grossly irregular ventricular rhythm with marked variability in QRS cycle length, morphology, and amplitude. "Functional analysis of the L-type calcium channel has shown that the CACNA1C R858H mutation associated with severe QT interval prolongation may lead to ventricular fibrillation (VF)." (PMID 29046645, 2017).
Parkinson disease (7 papers, 2015 to 2025). A progressive degenerative disorder of the central nervous system characterized by loss of dopamine producing neurons in the substantia nigra and the presence of Lewy bodies in the substantia nigra and locus coeruleus. "There is a great deal of evidence derived from knockout and cell based studies linkingAGER,CACNA1C andHMGB1 to Parkinson's pathogenesis.CACNA1C is also associated with circadian rhythm and narcolepsy." (PMID 34745571, 2020). "As an illustration, an aberrant relative abundance of alternatively spliced RNA isoforms of the SNCA, SRRM2, DAO, SHANK3, CACNA1C, and TSC2 genes has been observed in the brains of patients suffering from amyotrophic lateral sclerosis, autism spectrum disorder, and Parkinson’s disease." (PMID 39858933, 2025).
Ataxia (6 papers, 2019 to 2025). Ataxia refers to impaired coordination of voluntary muscle movement. "Considering the neurologically isolated presentation, CACNA1C mutation were recently found in a family with ataxia." (PMID 38790536, 2024). "The rs779393130 mutation of the CACNA1C gene co-segregated with the ataxia phenotype in this family." (PMID 31291898, 2019). "The heterozygote CACNA1C (rs779393130) variant, which co-segregated with the ataxia phenotype in the family, may be the mutation causing ADCA in this family." (PMID 31291898, 2019). "From the figures, it can be seen that differences related to ataxia are significant, and genes with strong correlations are VLDLR, ALDH5A1, and CACNA1C, and strong correlations means these correlations between gene variants and ataxia (or phenotype)." (PMID 31291898, 2019).